TGFB1 (transforming growth factor beta 1)
Diseases named in the same sentence as TGFB1 in open-access papers (continued):
Sharing a sentence is not in itself a finding about the gene and the disease.
tumor (continued). "Upregulation of TGFB1 has also been shown to dampen the body’s natural defenses against tumor cells, which in turn enhances tumorigenesis." (PMID 36830578, 2023). "Hypoxia in TME favors metastatic tumor cells for avoiding NK cell elimination by releasing TGFB1 and miRNAs through exosome to target NKG2D and trigger cell autophagy to block tumor cells to GZMB-mediated lysis." (PMID 37190251, 2023). "Immune-active subtypes are strongly associated with immune-active pathways and gene sets, and immune-depleted subgroups are closely related to tumor-promoting signals that restrain host immune response, like activation of the Wnt/TGFβ1 signaling pathway." (PMID 37351504, 2023). "Rab27a’s removal of exosomes stops tumor development and differentiation, suggesting that exosomal TGFβ1 is necessary for the creation of stroma that promotes the growth of tumors." (PMID 38202898, 2023). "If the monocytes were to differentiate into interleukin 4 (IL4), IL10/transforming growth factor beta 1 (TGFβ1) activated cells, it would trigger a regenerative response that would amplify the tumor growth." (PMID 38009543, 2023). "Exosomes promote angiogenesis and accelerate tumor development by inducing TGFβ1-dependent fibroblast transformation." (PMID 38202898, 2023). "Asporin is a stroma-derived inhibitor of TGFβ1 and a tumor suppressor in BC, where high asporin expression is significantly associated with less aggressive tumors when stratifying patients according to the clinical outcome." (PMID 37046676, 2023). "In the present study, PCDH10 overexpression significantly decreased the expression of genes associated with tumor progression and metastasis, including EREG, MMP1, MMP9, TGFB1, RASA4, and CXCL8, in GC cells." (PMID 37147733, 2023). "TGFβ1 is an immunosuppressive cytokine, which restricts T-cell infiltration to the tumor tissue in the tumor microenvironment." (PMID 38152616, 2023). "Since TGFβ1 acts as a tumor promoter in late-stage tumorigenesis by increasing angiogenesis and metastasis, lowering the level of TGFβ1 leads to inhibition of cancer cell proliferation." (PMID 37373289, 2023). "Whereas our results were based on bulk tumor transcriptomic profiling cohorts and the predictive value was focused on a single gene, which can hardly reflect the complex networks of TGFβ1 signaling and cell-to-cell communication." (PMID 37925591, 2023). "ILK expression is upregulated in human tumors and tumor cell lines, and its function is required for TGFβ-1-induced EMT in mammary epithelial cells." (PMID 37537585, 2023). "In murine cSCC, the effect of TGFβ1, being either tumor suppressive or tumor promoting, has been shown to depend on the stage of tumorigenesis." (PMID 37887285, 2023). "The expression of IFITM3 is positively correlated with Gleason score and T stage, and IFITM3 knockdown inhibits tumor cell migration and invasion; this inhibitory effect was more pronounced in transforming growth factor beta 1 (TGF-β1) pathway-activated cells." (PMID 37524814, 2023). "COL12A1+ fibroblasts highly expressed MMP2, MMP14, and TGFB1, which are related to tumor cell invasion and ECM degradation." (PMID 37430270, 2023). "The dysregulation of the TGFβ1 signalling pathway leads to tumour development and metastasis through the induction of EMT." (PMID 35406121, 2022). "Targeting FAP-expressing CAFs or TGFB1 signaling has been shown to mediate potent anticancer effects in a variety of preclinical tumor models." (PMID 36319998, 2022). "In our modeling genes, it has been shown that transforming growth factor β-inducible protein (TGFB1) can inhibit tumor progression by promoting apoptosis." (PMID 36406133, 2022).
tumor (continued). "We analyzed the TGFβ1 content in the tumor tissues and found that the amount of TGFβ1 decreased in the DETA-Dex group and the DETA-Dex/PD-1 inhibitor combination group compared with the group treated with only the PD-1 inhibitor." (PMID 36209170, 2022). "It is still controversial when and how the exercise interventions and inhibitors should be applied to perfectly suppress TGFβ-1 tumor-promoting signaling." (PMID 36518397, 2022). "Differentially expressed genes (DEGs) analysis showed a distinct transcriptional character in the CTCs although they shared some tumor-specific marker genes (such as TGFB1 and SOX9) with tumor cells in solid lesions." (PMID 35221332, 2022). "In contrast, tumor cells release transforming growth factor-beta 1 (TGF-1), which promote OV infection in CAFs." (PMID 36311790, 2022). "Combined blocking of TGFβ -activated kinase 1 (TAK1) and TGFBR1 inhibits IL1β/TGFβ1-mediated fibroblast activation, reduces secretion of pro-inflammatory cytokines and makes tumor cells more sensitive to chemotherapy." (PMID 35740594, 2022). "In the early stages of tumorigenesis, TGFβ1 acts as a tumor suppressor by inhibiting cell proliferation, inducing apoptosis, and suppressing growth factors, cytokine, and chemokine production." (PMID 35835840, 2022). "Further studies have shown that TGFβ/Smad pathway can be activated by platelet-secreted TGFβ1 and NF-κB pathway can be triggered by direct contact between tumor cells and platelets, and the latter can enhance the TGFβ1 transcriptional response of tumor cells." (PMID 35659308, 2022). "Tumor-derived EVs contain immunosuppressive molecules such as PD-L1, TGFβ1, FasL, TRAIL, and NKG2D ligands, which make them important mediators of tumor immune evasion." (PMID 35501802, 2022). "TGFβ1 is a highly immunosuppressive cytokine that contributes to tumor immune escape by inhibiting antitumor T-cell activity, thereby reducing the efficiency and efficacy of immunotherapies that involve the activation of T cells." (PMID 36209170, 2022). "The tumour immune environment contained high M2 macrophage infiltrate linked with MMP2, MMP14, TGFB1 and CCL2 expression, representing an immune suppressive environment." (PMID 35637530, 2022). "Compared with the direct involvement of IL6 in the process of bone destruction, TGFB1 mainly plays a role in the process of tumor bone metastasis." (PMID 35872837, 2022). "In contrast, Treg cells function as immune suppressors by inhibiting the activation of both CD4+ and CD8+ T cells, are generally found in higher numbers in tumor microenvironments, and secrete cytokines such as transforming growth factor-beta-1 (TGF-β1)." (PMID 36005179, 2022). "It is possible that rapid tumor growth noted in our study was attributable to the use of anti-PD-L1 therapy and by removal of circulating TGFβ1 and TGFβ2 with the TGFβ trap of BA." (PMID 36382087, 2022). "The tumours contain a high M2 macrophage infiltrate within the pleura and effusion TME, which is linked to high TGFB1 and CCL2 expression." (PMID 35637530, 2022). "TGFβ1, TGFβ2, and TGFβ3 protein expressions were distributed in similar regions, with higher levels in the cell cytoplasm, and a small amount in the tumor stroma." (PMID 36119489, 2022). "Tumor cells release transforming growth factor-beta 1 (TGF-β1), IL-4, IL-6, and IL-10 that educate TAM to polarize into M2 or become immunosuppressive." (PMID 36555392, 2022). "TGFβ1 overexpression can impair immune surveillance and promote angiogenesis, tumor invasion, and metastasis." (PMID 35835840, 2022).
tumor (continued). "Similar to MDSCs, CAFs secrete EVs with tumor-promoting potential, e.g., by transfer of TGFβ-1 and SMAD signaling activation driving EMT." (PMID 35563789, 2022). "Given the importance of WNT and TGFβ1 in mediating the crosstalk between tumor and stromal cells this work adds new insights in the mechanism of tumor angiogenesis and of its possible inhibition." (PMID 34478025, 2022). "Evidence indicates that TAB are able to negatively modulate the tumor-immune microenvironment mainly by upregulating the expression of transforming growth factor beta 1 (TGF-β1) and high mobility group box 1 (HMGB1) proteins in tumor cells." (PMID 36381212, 2022). "Subsequently, circulating Tregs are activated by tumor-derived suppressive factors (TDSFs), including IL-10 and TGFβ1, to promote an immunosuppressive environment that limits T effector functions and contributes to CTC survival." (PMID 35207611, 2022). "An additional qPCR analysis of the tumour cells showed significant increases in Il2, Ifng, Il1b, and Il18, and decreases in Il4, Il5, and Tgfb1, indicative of Th1‐dominant immune response." (PMID 35430766, 2022). "Hypoxia-inducible lipid droplet-associated (HILPDA) was overexpressed in multiple tumor types, HILPDA was positively correlated with tumor-associated macrophages (TAM) infiltration, and immunosuppressive genes, such as PD-L1, PD-1, TGFB1, and TGFBR1." (PMID 36439512, 2022). "To verify the role of TGFβ1 in the CP-mediated antitumor effects, we constructed a 4T1 cell tumor mouse model with TGFβ1 knockout." (PMID 36209170, 2022). "CAF-educated myeloid cells are transformed into pro-tumor macrophages, leading to the suppression of T cell proliferation by upregulating TGFB1 expression and IL10 production." (PMID 35455650, 2022). "Considerable research attention has been focussed on a role of deregulation of Transforming Growth Factor β1 (TGFβ1) as tumor promoter step favoring BC invasion and metastasis." (PMID 35658894, 2022). "Since transforming growth factor‐beta 1 (TGF‐β1) has been identified as one of the critical factors of bad prognosis in many tumor types, TGF‐β1 blockades have emerged as a potential cancer therapy strategy." (PMID 37693065, 2022). "Cancer-associated fibroblasts play a crucial role in the development of desmoplastic reaction and shape the tumor immune microenvironment by the expression of immunoregulatory molecules such as TGFB1 (transforming growth factor-beta)." (PMID 35392092, 2022). "The lower the degree of cell differentiation and the more malignant tumor forms, the higher TGFβ1 expression levels were observed." (PMID 35454784, 2022). "The results showed that the serum TGFB1 level and the activity of the TGFB1 signaling pathway were significantly increased in tumor patients with bone metastases." (PMID 35872837, 2022). "Specifically in tumours, autocrine and paracrine stimulation of cancer cells by cytokines such as TGFβ1 induce EMT while promoting an immunosuppressive microenvironment." (PMID 35203300, 2022). "TGFβ1 is the driver and primary mediator of changes in the tumor microenvironment and is a critical factor that limits the efficacy of checkpoint inhibitor therapy for patients with several types of solid tumors." (PMID 35646681, 2022). "TGFB1 was found to exert its pro‐metastatic function by affecting the crosstalk between tumor and endothelial cells, thereby promoting angiogenesis." (PMID 35791509, 2022). "The previously defined HCC immune-exhausted subclass is characterized by active tumour stroma, enrichment of the TGFβ1 pathway, and the poorest patient prognosis." (PMID 36589727, 2022). "For example, some SASP‐associated factors, such as vascular endothelial growth factor (VEGF), endothelial growth factor (EGF) and transforming Growth Factor Beta 1 (TGFβ1), promote tumorigenesis and tumour progression." (PMID 35674055, 2022).
tumor (continued). "TGFβ1 is a crucial metabolic driver in tumor-adjusting metabolic pathways for neoplastic metastasis and CSC formation in the TME." (PMID 36474273, 2022). "In metazoan biology, the role of regulatory cytokine TGFβ-1 signaling pathway is substantial, however its dysregulation results in tumor development." (PMID 36518397, 2022). "Tumor cells also seem to be more invasive and more likely to metastasize in the setting of TGFB1 overexpression." (PMID 36149322, 2022). "Together, these data suggested that the immune activation and antitumor effects of CP treatment were probably mediated by CP-triggered LLPS and TGFβ1 downregulation in the tumor cells." (PMID 36209170, 2022). "During early tumor outgrowth, TGFβ-1 acts as a tumor suppressor, but becomes a tumor promoter at later stages through enhancing tumor cell mobility, invasion and metastasis." (PMID 36518397, 2022). "TGFB1 acts as a tumor suppressor in the early stage of tumors or normal tissues and promotes tumorigenesis and metastasis in advanced tumors." (PMID 35593122, 2022). "TGFB1 encoded transforming growth factor-β (TGF-β) and FAP coded fibroblast activation protein alpha (FAP), both of which took part in disabling anti-tumor immune cells and impeding infiltration of immune cells." (PMID 35646049, 2022). "Vice versa, overexpression of KIT caused a partial epithelial-to-mesenchymal phenotype switch, a strong increase of intra-tumor stromal content, and high expression of TGFβ1." (PMID 35842424, 2022). "Bone metastasis tumour cells exit from dormancy can be influenced by factors produced during osteoclast-mediated bone resorption, including TGFβ1 and MMP-9." (PMID 36307871, 2022). "We found that TGFB1 and its binding partner ENG were both highly expressed in tumor cells and TGFB1-ENG gene pair occupied a key position in the network." (PMID 36249427, 2022). "Transforming growth factor β1 (TGFβ1), a dichotomous cytokine, acts as a tumor suppressor or tumor promoter in different circumstances." (PMID 35399527, 2022). "Subsequently, these activated bone cells also secrete tumor growth promoting factors like TGFβ1, to advocate tumor growth and, ultimately, form a positive feedback loop." (PMID 35207611, 2022). "The first of such cytokines is transforming growth factor β1 (TGFβ1) which is produced excessively by tumour cells and results in downregulation of NKp30 and NKG2D NK cells activation receptors." (PMID 35806034, 2022). "These EV-mediated effects were dependent on TGFβ-1 and IL-10, as neutralising antibodies specific for these cytokines blocked the ability of tumor-derived EVs to expand Treg cells." (PMID 35563789, 2022). "The growth of the tumors with TGFβ1 knockout was significantly decreased compared with mice with normal 4T1 cells, and TGFβ1 protein supplementation was able to recover the growth capacity of the tumor." (PMID 36209170, 2022). "Granulocyte-macrophage colony-stimulating factor (GM-CSF), tumor necrosis factor alpha (TNF-α), and transforming growth factor-beta 1(TGFβ1) promote tumor cell proliferation and survival." (PMID 36387244, 2022). "PDK1 and PDK2 were knocked down by the lentivirus shRNA system to investigate their role in TGFβ1-promoted tumor progression in vitro." (PMID 36474273, 2022). "Second, treatment with all three different CPs significantly decreased TGFβ1 expression in the tumor tissue." (PMID 36209170, 2022). "Mechanistically, there was increased expression of PD-1, FOXP3 (forkhead box P3), and TGFβ1, key players in the tumor immune evasion response, while genes involved in the inflammatory response, such as IL2 and interferon (IFN)γ, were downregulated." (PMID 36233088, 2022). "The analyses performed in this study concluded that the expression of TGFβ1 and TGFβ2 increased with increasing tumor grade and, thus, malignancy." (PMID 35454784, 2022).
tumor (continued). "MATN2 is localized downstream of several growth factor receptors, such as IGF-1R, GPER, and TGFβ1, and involved in tumor progression by stimulating the growth, chemotaxis, and migration of cancer cells." (PMID 35976950, 2022). "We found that the high-risk group was significantly associated with higher expression level of immune checkpoints and immune inhibitory factors, including CCL2, CTLA4, CXCR4, IL6, LAG3, PDCD1, and TGFB1, indicating tumor immune evasion." (PMID 36092894, 2022). "GSC migration and invasion can be promoted by soluble factors from the tumor microenvironment, such as transforming growth factor beta 1 (TGF-β1) and adenosine." (PMID 35205179, 2022). "Studies predominantly reveal tumour intrinsic resistant mechanisms to growth inhibitory or proapoptotic effects of TGFB1." (PMID 35406544, 2022). "During melanoma formation, TGFβ1-overactivated CD133+CSCs have been shown to recruit the immunosuppressive MDSCs in the tumor site." (PMID 35395787, 2022). "We found that UCK2 was responsive to TGFβ1 stimulation implying the crosslink between microenvironment and tumour cell in the initial stages of tumour formation." (PMID 36447138, 2022). "RE cell heterogeneity was stably maintained for long periods after TGFβ1 removal both in vitro and in large tumours derived from the nude mice." (PMID 36101425, 2022). "Thrombospondin-1 (Tsp-1) secreted from quiescent endothelial cells promotes dormancy, whereas in sprouting endothelial cells, TGFβ1 and Periostin secreted from endothelial tip cells promote tumor cell outgrowth." (PMID 35418981, 2022). "For example, senescent thyroid tumor cells can induce M2-macrophages polarization with increased expression of CCL17,CCL18,IL-18,TGFβ1, that ultimately promotes tumor migration by activating NF-κB signaling pathway." (PMID 35479325, 2022). "We evaluated the expression of TGFβ1 in cancer cells alone in the immunohistochemical staining, and the TCGA data included the information from both cancer cells and tumor stromal cells." (PMID 35650563, 2022). "TGFβ1 is a cytokine that functions as a tumor suppressor in the early stages of tumor progression and as an oncogene during advanced stages of tumors." (PMID 35659780, 2022). "Treatment of human COV434 cells with TGFβ1 enhances cell viability and reduces apoptosis, favoring tumor development." (PMID 35565312, 2022). "Changes in the TGFβ1-pSMAD2/3 pathway significantly can affect the proliferation, migration and invasion of tumour cells." (PMID 35186724, 2022). "TGFβ1 was present in the cytoplasm of both tumor cells and stromal cells whereas Collagen type I, an ECM protein, was present in the stroma with the mesenteric mass containing more stroma compared to the primary tumor." (PMID 33718208, 2021). "The dual complexity of the functions of TGFβ1 in tumors, and the link between tumor progression and TGFβ1 in cancer stroma has warranted profound investigation." (PMID 34095135, 2021). "More specifically, studies carried out in mouse models with cSCC have proven that TGFβ1 mediates tumor resistance to different chemotherapeutic agents." (PMID 34830768, 2021). "Overall, our data show that conditional activation of TGFβ1 in c-Myc positive HCC cells contributes to tumor metastasis in vitro and in vivo." (PMID 33608500, 2021). "These factors resulted in profound changes in the composition of the tumour stroma, rendered the CAFs resistant to gemcitabine and drove further TGFβ1 release." (PMID 34638468, 2021). "Tumor microenvironment is inflammatory and known to express higher levels of growth and cell transformation factors such as TGFβ1 and EGF, and/or their receptors." (PMID 33889303, 2021). "Tumor and tumor stroma were subjected to multiplex immunohistochemistry to quantitate TGFβ1 and other immune factors in CAFs." (PMID 34095135, 2021). "Integrins αV and β3 mediate TGFβ1 (a transforming growth factor β1-induced extracellular matrix protein)-induced endogenous anti-tumour and antiangiogenic properties." (PMID 33799345, 2021).